XIRP1 (xin actin binding repeat containing 1)
Description:
Protects actin filaments from depolymerization. Required for correct cardiac intercalated disk ultrastructure via maintenance of cell-cell adhesion stability, and as a result maintains cardiac organ morphology, conductance and heart beat rhythm (By similarity). Required for development of normal skeletal muscle morphology and muscle fiber type composition (By similarity). Plays a role in regulating muscle satellite cell activation and survival, as a result promotes muscle fiber recovery from injury and fatigue (By similarity).
Synonyms: CMYA1; XIN; DKFZp451D042
Tractability: PROTAC: ubiquitination databases record sites on it.
Gene: Protein-coding gene on chromosome 3 (39,183,210 to 39,192,599, reverse strand). Ensembl gene ENSG00000168334.
Subcellular location: Cell junction, adherens junction; Cell junction, desmosome
Subcellular location (Human Protein Atlas): Actin filaments; Nucleoplasm
Gene Ontology:
Molecular function: actin filament binding; protein binding; RNA binding; actin binding
Biological process: actin filament organization; negative regulation of protein binding; intracellular protein localization; myoblast differentiation involved in skeletal muscle regeneration; satellite cell activation involved in skeletal muscle regeneration; actin cytoskeleton organization
Cellular component: focal adhesion; nucleoplasm; stress fiber; adherens junction; cell junction; desmosome
Genetic constraint (gnomAD): Missense variants: 2,116 observed, 2,164.8 expected, observed/expected ratio (o/e) 0.98, 90% interval 0.94 to 1.01. Synonymous variants: 884 observed, 877.38 expected, observed/expected ratio (o/e) 1.01, 90% interval 0.95 to 1.07.
Homologues: Orthologues: dog XIRP1 (76% identical), rabbit XIRP1 (71% identical), mouse Xirp1 (70% identical), rat Xirp1 (68% identical), chimpanzee XIRP1 (60% identical), tropical clawed frog xirp1 (31% identical), zebrafish xirp1 (29% identical). Paralogues in human: XIRP2 (24% identical).
Diseases named in the same sentence as XIRP1 in open-access papers:
XIRP1 is named in the same sentence as 19 diseases in open-access papers, as found by Europe PMC text mining. Sharing a sentence is not in itself a finding about the gene and the disease. The quoted sentences say what the papers report.
cardiomyopathy (2 papers, 2020 to 2021). A disease of the heart muscle or myocardium proper. "In contrast, the Xirp1 null mutant phenotype was characterized by a late-onset cardiomyopathy with conduction defects." (PMID 33261556, 2020). "Knockout Xirp1 (or Xinα) mice develop a late-onset cardiomyopathy with conduction defects." (PMID 33261556, 2020). "The regulatory roles of other enriched genes in cardiomyopathy networks (including SYNE2, APOB, XIRP1, ALPK3, and LRPPRC) are not clear." (PMID 34236536, 2021).
Hypertension (2 papers, 2020 to 2021). The presence of chronic increased pressure in the systemic arterial system. "Certain genes involved in the pathogenesis of hypertension—Alb, Chrm2, Xirp1, Kcnq1, Slc5a7, Kcnh1, Ache, Crlf1 and Galr2— should also be studied." (PMID 34603037, 2021). "Previous studies have shown that the XIRP1 gene is related to hypertension and nervous system development." (PMID 33072571, 2020).
autism (1 paper, 2014). Persistent deficits in social interaction and communication and interaction as well as a markedly restricted repertoire of activity and interest as well as repetitive patterns of behavior. "However, rs4453791 is also related to non-coding functional variation near CCSRN1 and XIRP1, the latter being an autism susceptibility locus of weak candidacy." (PMID 24564958, 2014).
cardiac arrhythmia (1 paper, 2020). Any disturbances of the normal rhythmic beating of the heart or MYOCARDIAL CONTRACTION. "Missense mutations in XIRP1 cause cardiac arrhythmias and a number of mutations in XIRP1 that are classed as deleterious have been found in patients with conditions including myalgia, proximal weakness, arrhythmia, contractures and cardiac conduction defects." (PMID 33261556, 2020). "Mutations in human POPDC1, POPDC2 and in human XIRP1, all cause pathological cardiac arrhythmias, suggesting a possible role for POPDC1/2 and XIRP1 interaction in normal cardiac conduction." (PMID 33261556, 2020).
congenital muscular dystrophy (1 paper, 2014). A muscular dystrophy that is characterized by diminished muscle tone (hypotonia), progressive muscle weakness and degeneration (atrophy), abnormally fixed joints, spinal rigidity, and delays in reaching motor milestones such as sitting or standing unassisted. "The gene XIRP1, matching the locus for hyalin body myopathy and congenital muscular dystrophy with joint hyperlaxity, was originally studied in relation to murine cardiac morphogenesis and later shown to bind skeletal muscle actin in in vitro assays." (PMID 25353622, 2014).
diabetic (1 paper, 2021). "Consistent with our results, survey of microarray datasets in Gene Expression Omnibus (GEO) has revealed that XIRP1 downregulated in failing hearts from human patients with diabetic or non-diabetic heart failure (GDS4314), and idiopathic DCM (GDS651)." (PMID 34222259, 2021).
epilepsy (1 paper, 2024). A brain disorder characterized by episodes of abnormally increased neuronal discharge resulting in transient episodes of sensory or motor neurological dysfunction, or psychic dysfunction. "Genes differentially expressed in human TLE samples and previously implicated in epilepsy (XIRP1, CCL2, and NPAS4), were predicted to have potential methylation sites and showed inverse expression changes to those found for snoRNAs in human TLE." (PMID 39509000, 2024).
kidney stones (1 paper, 2018). "Xirp1 might play an important role in the pathology of kidney stones." (PMID 30200873, 2018).
lung adenocarcinoma (1 paper, 2020). A carcinoma that arises from the lung and is characterized by the presence of malignant glandular epithelial cells. "Finally, hub IRGs CLEC17A, INHA, and XIRP1 were considered novel prognostic biomarkers for lung adenocarcinoma." (PMID 33072571, 2020).
melanoma (1 paper, 2020). A malignant, usually aggressive tumor composed of atypical, neoplastic melanocytes. "Next, we validated the highest significantly down- (Myh2, Mybh, Sypl2, Xirp1, Mybpc1) and up- (Fcgbp, Areg) regulated genes, including the melanoma-specific genes (Dmnt1 and Nrp2) identified by RNA sequencing following treatment with SAM+anti-PD-1 by RT-qPCR." (PMID 32983966, 2020).
muscular dystrophy (1 paper, 2012). Muscular dystrophy (MD) refers to a group of more than 30 genetic diseases characterized by progressive weakness and degeneration of the skeletal muscles that control movement. "Further functional long-term assessments of the role of Xirp1 in different disease or injury conditions such as muscular dystrophy models are warranted." (PMID 22355335, 2012).
sarcopenia (1 paper, 2025). Progressive decline in muscle mass due to aging which results in decreased functional capacity of muscles. "In secondary sarcopenia models, ST revealed early atrophy markers such as Xirp1, Cryab, and polyamine-pathway enzymes selectively enriched in glycolytic regions, suggesting spatially restricted intervention points." (PMID 40718353, 2025).
myopathies (2 papers, 2018 to 2020). "Xirp1 in particular has been found up-regulated in injured muscle and myopathy and both Nrap and Xirp1 were associated with plaques in myofibrillar myopathies (MFMs)." (PMID 30089464, 2018).
bacterial infections (1 paper, 2025). "XIRP1 is a protein-coding gene expressed mainly in fibroblasts and macrophages in response to cytokines and bacterial infections such as Listeria, Shigella, and Salmonella." (PMID 40070201, 2025).
XIRP1 also shares sentences with these, for which no sentence is quoted: heart disease (2 papers); heart failure (1); hyalin body myopathy (1); Onset (1); vitiligo (1).